BLOC1S4 (biogenesis of lysosomal organelles complex 1 subunit 4)
Description:
Component of the BLOC-1 complex, a complex that is required for normal biogenesis of lysosome-related organelles (LRO), such as platelet dense granules and melanosomes. In concert with the AP-3 complex, the BLOC-1 complex is required to target membrane protein cargos into vesicles assembled at cell bodies for delivery into neurites and nerve terminals. The BLOC-1 complex, in association with SNARE proteins, is also proposed to be involved in neurite extension. Plays a role in intracellular vesicle trafficking.
Synonyms: CNO; FLJ11230; BCAS4L; BLOS4
Tractability: PROTAC: its protein half-life has been measured.
Gene: Protein-coding gene on chromosome 4 (6,716,174 to 6,717,664, forward strand). Ensembl gene ENSG00000186222.
Subcellular location: Cytoplasm
Subcellular location (Human Protein Atlas): Vesicles; Cytosol
Pathways (Reactome):
Vesicle-mediated transport: Golgi Associated Vesicle Biogenesis
Gene Ontology:
Molecular function: protein binding; AP-3 adaptor complex binding
Biological process: anterograde axonal transport; anterograde synaptic vesicle transport; melanosome organization; neuron projection development
Cellular component: BLOC-1 complex; cytoplasm; cytosol; axon cytoplasm
Genetic constraint (gnomAD): Loss-of-function variants: 4 observed, 2.25 expected, observed/expected ratio (o/e) 1.78, 90% interval 0.71 to 1.95. That is too few expected variants to judge how well the gene tolerates losing a copy. Missense variants: 332 observed, 265.43 expected, observed/expected ratio (o/e) 1.25, 90% interval 1.14 to 1.37. Synonymous variants: 179 observed, 121.52 expected, observed/expected ratio (o/e) 1.47, 90% interval 1.3 to 1.67.
Homologues: Orthologues: chimpanzee BLOC1S4 (100% identical), macaque BLOC1S4 (97% identical), dog BLOC1S4 (80% identical), pig BLOC1S4 (78% identical), rat Bloc1s4 (78% identical), mouse Bloc1s4 (77% identical), tropical clawed frog bloc1s4 (42% identical), zebrafish bloc1s4 (40% identical), Drosophila melanogaster Blos4 (19% identical). Paralogues in human: BCAS4 (30% identical).
Diseases named in the same sentence as BLOC1S4 in open-access papers:
BLOC1S4 is named in the same sentence as 4 diseases in open-access papers, as found by Europe PMC text mining. Sharing a sentence is not in itself a finding about the gene and the disease. The quoted sentences say what the papers report.
Hermansky-Pudlak syndrome (2 papers, 2017 to 2025). Hermansky-Pudlak syndrome (HSP) is a multi-system disorder characterized by oculocutaneous albinism, bleeding diathesis and, in some cases, neutropenia, pulmonary fibrosis, or granulomatous colitis. "Indeed, human mutations in BLOC1S4 are associated with Hermansky-Pudlak Syndrome, a genetic disorder characterized by defects in lysosome-related organelles, while SCARB2 is necessary for lysosomal membrane integrity." (PMID 40813676, 2025).
BLOC1S4 also shares sentences with these, for which no sentence is quoted: genetic disorder (1 paper); melanoma (1); ovarian carcinoma (1).